MBD2 (methyl-CpG binding domain protein 2)
Description:
Binds CpG islands in promoters where the DNA is methylated at position 5 of cytosine within CpG dinucleotides. Binds hemimethylated DNA as well. Recruits histone deacetylases and DNA methyltransferases to chromatin. Acts as a component of the histone deacetylase NuRD complex which participates in the remodeling of chromatin. Acts as a transcriptional repressor and plays a role in gene silencing. Functions as a scaffold protein, targeting GATAD2A and GATAD2B to chromatin to promote repression. May enhance the activation of some unmethylated cAMP-responsive promoters.
Synonyms: DMTase; NY-CO-41
Tractability: Small molecule: a high-quality ligand is known. PROTAC: ubiquitination databases record sites on it; its protein half-life has been measured; a small molecule that binds it is known.
Target class: Epigenetic regulator; Reader; Methyl-CpG-binding domain
Gene: Protein-coding gene on chromosome 18 (54,151,606 to 54,224,669, reverse strand). Ensembl gene ENSG00000134046.
Subcellular location: Nucleus; Chromosome
Subcellular location (Human Protein Atlas): Nucleoplasm
Pathways (Reactome):
Chromatin organization: Interaction of NuRD complexes with transcription factors; NuRD complex assembly
Gene expression (Transcription): NoRC negatively regulates rRNA expression; RNA Polymerase I Promoter Opening
Gene Ontology:
Molecular function: C2H2 zinc finger domain binding; methyl-CpG binding; molecular adaptor activity; nucleosomal DNA binding; protein binding; protein domain specific binding; satellite DNA binding; chromatin binding; DNA binding; identical protein binding; mRNA binding; siRNA binding
Biological process: chromatin remodeling; DNA methylation-dependent constitutive heterochromatin formation; negative regulation of transcription by RNA polymerase II; negative regulation of DNA-templated transcription; positive regulation of DNA-templated transcription; cellular response to serotonin; embryonic organ development; epigenetic regulation of gene expression; maternal behavior; regulation of transcription by RNA polymerase II; response to bisphenol A; response to estradiol; response to mechanical stimulus; response to nutrient levels; ventricular cardiac muscle tissue development
Cellular component: chromatin; chromosome; nucleoplasm; nucleus; NuRD complex; protein-containing complex; cytoplasm; heterochromatin; histone deacetylase complex
Genetic constraint (gnomAD): Loss-of-function variants: 7 observed, 24.38 expected, observed/expected ratio (o/e) 0.29, 90% interval 0.16 to 0.54. The upper end of that interval is the gene's LOEUF score, 0.54, which puts it in group 2 of 6, group 1 being the genes least tolerant of losing a copy. Missense variants: 345 observed, 360.01 expected, observed/expected ratio (o/e) 0.96, 90% interval 0.88 to 1.05. Synonymous variants: 170 observed, 139.68 expected, observed/expected ratio (o/e) 1.22, 90% interval 1.07 to 1.38.
Homologues: Orthologues: macaque MBD2 (99% identical), dog MBD2 (98% identical), mouse Mbd2 (97% identical), rat Mbd2 (96% identical), chimpanzee MBD2 (84% identical), rabbit MBD2 (76% identical), guinea pig MBD2 (74% identical), pig MBD2 (59% identical), tropical clawed frog mbd2 (56% identical), Drosophila melanogaster MBD-like (26% identical). Paralogues in human: MBD3 (47% identical), MBD1 (21% identical), MBD3L1 (19% identical), MBD3L2 (16% identical), MBD3L2B (16% identical), MBD3L3 (16% identical), MBD3L4 (16% identical), MBD3L5 (16% identical).
Diseases named in the same sentence as MBD2 in open-access papers:
MBD2 is named in the same sentence as 120 diseases in open-access papers, as found by Europe PMC text mining. Sharing a sentence is not in itself a finding about the gene and the disease. The quoted sentences say what the papers report.
breast cancer (35 papers, 2003 to 2025). A primary or metastatic malignant neoplasm involving the breast. "MBD2 Mediates transcriptional repression associated with hypermethylated GSTP1 CpG islands in MCF-7 breast cancer cells." (PMID 38711004, 2024). "Since the gene is knocked out before conception, gene loss certainly precedes tumor initiation; thus, the study design allows conclusions to be drawn regarding the causal role of Mbd2 in breast cancer." (PMID 38556549, 2024). "Methyl-CpG-binding domain protein 2 (Mbd2), a reader of DNA methylation, has been implicated in different types of malignancies, including breast cancer." (PMID 38556549, 2024). "In line with this, the MBD2 regulon was downregulated in response to infection but upregulated in breast cancer‐associated macrophages, showing the opposite pattern to the IRF8 regulon." (PMID 37073532, 2023). "We further find an enrichment of the M2 gene set among the MBD2 regulon in breast cancer associated macrophages." (PMID 37073532, 2023). "Analysis of single nucleotide polymorphisms in MBD2 in breast cancer patients were similarly difficult to interpret, although some weak associations were detected." (PMID 27303433, 2016). "MBD2 was previously implicated in cancer growth and metastasis in several types of cancers including breast cancer." (PMID 24204564, 2013). "Methyl-CpG-binding domain protein-2 (gene X99687) mediates transcriptional repression associated with hypermethylated GSTP1 CpG islands in MCF-7 breast cancer cells." (PMID 17316436, 2007). "The present case-control study investigated associations between two single nucleotide polymorphisms (SNPs) in the MBD2 gene and breast cancer risk." (PMID 16168120, 2005). "Since results obtained via these methodologies are highly confounded, the main outstanding question was whether Mbd2 plays a causal role in breast cancer." (PMID 38556549, 2024). "Rabbani and colleagues demonstrated that MBD2 promotes breast cancer progression through the modulation of the epithelial-to-mesenchymal transition." (PMID 41258082, 2025). "In conclusion, the results of the present study indicate that Mbd2 coordinately activates and suppresses gene expression programs leading to tumor growth and metastasis, identifying it as a candidate target for breast cancer therapeutics." (PMID 38556549, 2024). "Our data demonstrate that PyMT oncogene-driven spontaneous mammary tumor formation is delayed upon homozygous deletion of the Mbd2 gene." (PMID 38556549, 2024). "Herein, using a molecular genetics approach in transgenic MMTV-PyMT mice, we demonstrated that Mbd2 deletion significantly decreases mammary tumor growth and metastasis." (PMID 38556549, 2024). "This research looked at the role of Methyl-CpG-Binding Domain Protein 2 (MBD2), a protein that interprets these methylation signals, in breast cancer." (PMID 38556549, 2024). "Since Mbd2-depleted mice are viable and fertile, testing whether targeting Mbd2 and/or its ability to bind methylated DNA produces a similar anticancer effect in patients with breast cancer to reduce cancer-associated morbidity and mortality would be similarly attractive." (PMID 38556549, 2024). "For example, Mbd2 deletion decreased the expression of Gsn (encoding Gelsolin), a protein involved in TGF-β-mediated induction of EMT in breast cancer." (PMID 38556549, 2024). "Taken together, the results of this study provide a rationale for further development of epigenetic therapies targeting Mbd2 to inhibit the progression of breast cancer." (PMID 38556549, 2024).
breast cancer (continued). "Hypoxia-driven preferential splicing of the methyl-CpG binding domain protein 2 (MBD2) gene to the MBD2a isoform promotes breast cancer metastasis." (PMID 37583933, 2023). "We have reported similar findings in breast cancer cell lines in which MBD2 depletion results in transcriptional activation of silenced, methylated tumor suppressor genes without loss of corresponding promoter methylation." (PMID 37307480, 2023). "Stable knockdown of the MBD2 gene suppressed the proliferation of several breast cancer cell lines in vitro and decreased tumor volume in vivo." (PMID 31245293, 2019). "Methylated DNA binding domain protein 2 (MBD2) is known as the only TF of miR-496, which coordinately silences gene expression through activation of the miR-496 promoter in breast cancer cell line." (PMID 28651018, 2017). "The Double Mutant MBD2Flag construct was expressed in a background of partial knockdown of endogenous MBD2 in MDA-MB-435 breast cancer cells." (PMID 25753662, 2015). "Mutating these residues abrogates interaction of MBD2 with the histone deacetylase core and impairs the ability of MBD2 to repress the methylated tumor suppressor gene PRSS8 in MDA-MB-435 breast cancer cells." (PMID 25753662, 2015). "It is surprising therefore that this gene is down regulated by MBD2 and hsa-mir-496 in highly invasive breast cancer cells MDA-MB-231." (PMID 24204564, 2013). "We also show in two breast cancer cell lines that endogenous MBD2 is required for expression of hsa-mir-496 since depletion of MBD2 results in reduction of hsa-mir-496 expression." (PMID 24204564, 2013). "Second, expression of hsa-mir-496 is partially dependent on endogenous MBD2 in two breast cancer cell lines; partial depletion of MBD2 results in reduction in hsa-mir-496 expression." (PMID 24204564, 2013). "Hypermethylation of CpG dinucleotides at the 5′ transcriptional regulatory region has been shown to be sufficient to inhibit GSTP1 transcription in the MCF-7 breast cancer cell line when mediated by the methyl-CpG-binding domain (MBD) protein MBD2." (PMID 16434992, 2006). "MBD2 has also been reported to be involved in the repression of GSTP1 transcription in breast cancer cells." (PMID 16168120, 2005). "One interesting finding from that study was that breast carcinomas can be divided into two groups, with one expressing very high levels of MBD2 and the other expressing a much lower level." (PMID 16168120, 2005). "The MBD2 gene deletion impairs PI3K/Akt pathway activation in breast cancer." (PMID 40467564, 2025). "The research suggests that focusing on MBD2 could be a possible treatment approach for breast cancer." (PMID 38556549, 2024). "To test whether Mbd2 plays a role in prolonging the survival of mammary tumor-bearing mice, we kept several mice from each group beyond the experimental endpoint at week 20 (after birth)." (PMID 38556549, 2024). "Moreover, Mbd2 knockdown partially blocked the TGF-β-induced increase in the invasiveness of breast cancer cells in vitro." (PMID 38556549, 2024). "It was found that MBD2 is overly active in several kinds of cancer, including breast cancer." (PMID 38556549, 2024). "Next, to rule out any species-specific idiosyncrasy, we sought to assess whether MBD2 plays a similar role in mediating EMT in human breast cancer cells." (PMID 38556549, 2024). "From our correlation analysis of gene and protein expression we have observed that out of these three MBD proteins only MBD2 gene regulate the BRCA1 gene expression in ER+ & PR+ & Triple negative breast cancer cells, others only have regulation in ER+ & PR+ breast cancer cells." (PMID 38711004, 2024). "To this end, we used CRISPR interference to deplete MBD2 in human MDA-MB-231 breast cancer cells." (PMID 38556549, 2024).
breast cancer (continued). "In 5-azaCdR-induced breast cancer, MBD2 depletion can inhibit cell invasion." (PMID 34671397, 2021). "Furthermore, it was demonstrated that tumor suppressor genes like DAPK1 and KLK10 are de-repressed upon depletion of MBD2 in breast cancer cells." (PMID 31245293, 2019). "However, previous studies have shown that MBD2 is required for the activation and maintenance of a demethylated state of prometastatic genes in liver, prostate, and breast cancers." (PMID 26788506, 2015). "MBD2-NuRD has been established as a transcriptional repressor of embryonic and fetal β-type globin genes in primary adult erythroid cells across different species and of tumor suppressor genes in breast cancer cells." (PMID 25753662, 2015). "This suggests that MBD2 may bind at these loci in breast cancer instigated by increased methylation." (PMID 24927503, 2014). "To determine whether endogenous MBD2 plays a role in hsa-mir-496 DNA methylation we measured the effects of depletion of MBD2 mRNA in two breast cancer cell lines MCF-7 and MDA-MB-231 that express significant levels of MBD2." (PMID 24204564, 2013). "Interestingly, down regulation of MBD2 was previously shown to reverse invasiveness and metastasis in breast cancer and prostate cancer cell lines." (PMID 24204564, 2013). "Interestingly, different sites are impacted in response to MBD2 depletion in different breast cancer cell lines." (PMID 24204564, 2013). "A significant reduction in the level of MBD2 mRNA expression was found in human colorectal and gastric tissues compared with nonmalignant tissues, whereas elevated expression was reported in breast cancer." (PMID 18414412, 2008). "Findings from the present study show associations between genotypes and haplotypes of the MBD2 gene and breast cancer, which have not previously been examined." (PMID 16168120, 2005). "Our results demonstrate significant associations between MBD2 genotypes and haplotypes and breast cancer risk in premenopausal women but not in postmenopausal women." (PMID 16168120, 2005). "For example, a recent study showed that breast carcinomas exhibit alterations in MBD2 expression." (PMID 16168120, 2005). "SFRPs interact with FZDs, and MBD2 alternative splicing inhibits FZD1 activation under hypoxic conditions, thereby promoting breast cancer metastasis." (PMID 40860197, 2025). "Moreover, changes in the promoter methylation status of the Cdh2 and Spp1 genes, as a direct or indirect effect of Mbd2 deletion and subsequent binding by a transcriptional repressor, may also constitute a possible mechanism for regulating these genes in breast cancer." (PMID 38556549, 2024).
breast cancer (continued). "Estrogen enhanced the promoters of DNMT3B, MBD2, and HDAC1 in breast cancer cells and reduced COMT transcription, resulting in increased DNA oxidative damage." (PMID 35211407, 2022). "This study's aim was to identify MBD2 as biomarker which regulate the BRCA1 and p16 gene expression in MCF‐7 breast cancer cells by Real Time PCR." (PMID 29460395, 2018). "In human mammary cancer cell lines, the repression of DAPK1 mediated by MBD2 seems to actively participate in maintenance of their aggressive phenotypes when xenografted into immuno-deficient mice." (PMID 26007656, 2015). "Overexpression of MBD2 in breast epithelial cell line MCF-10A results in induced expression and demethylation of hsa-mir-496 while depletion of MBD2 in a human breast cancer cell lines MCF-7 and MDA-MB231 results in suppression of hsa-mir-496." (PMID 24204564, 2013). "The identification of MBD2 as a negative regulator of BRCA1 expression, along with the functional consequences on cell behavior, adds depth to our understanding of epigenetic and pharmacological interventions in breast cancer." (PMID 38711004, 2024). "MBD2 has regulatory role in BRCA1 gene expression and could be used as biomarker for breast cancer and targeted by drug combination therapy." (PMID 29460395, 2018). "Methylated DNA fragments were selected using a recombinant protein containing the Methyl‐CpG‐binding domain of MBD2 of MBD2 (Methyl‐Cap‐seq), from MDA‐MB‐231 cell line derived from human breast cancer, and the HMLER cell line constructed from in vitro transformation of human mammary cells." (PMID 27378792, 2016). "To test this hypothesis, we assayed the expression of a previously identified highly methylated MBD2 target gene, PRSS8, in MDA-MB-435 breast cancer cells." (PMID 25753662, 2015). "These tagged-MBD2 binding sites in MCF-7 show increased methylation in a cohort of primary breast cancers but not in normal breast samples, suggesting a putative role for MBD2 in breast cancer." (PMID 24927503, 2014). "Regions bound by MBD2 in MCF-7 show overall increased methylation levels in a large set of primary breast cancer samples but not in a model of non-cancer human mammary epithelial cells." (PMID 24927503, 2014). "MBD2 has been reported to mediate epigenetic silencing of 14-3-3σ in TRAMP C1 cells and human LNCaP prostate cells, and has been shown to be involved in the transcriptional repression of GSTP1 in MCF-7 breast cancer cells." (PMID 20062804, 2010). "In conclusion MBD2 protein interact to the BRCA1 gene promoter, and resveratrol modulates MBD2 gene expression, which in turn regulates BRCA1 gene expression, and inhibits cell proliferation, migration, and induces apoptosis in ER+, PR+ & Triple negative breast cancer cells." (PMID 38711004, 2024). "To test whether Mbd2 plays a causal role in mammary tumor growth and metastasis, we performed genetic knockout (KO) of Mbd2 in MMTV-PyMT transgenic mice and compared mammary tumor progression kinetics between the wild-type (PyMT-Mbd2+/+) and KO (PyMT-Mbd2−/−) groups." (PMID 38556549, 2024).